RACK1 (receptor for activated C kinase 1)
Diseases named in the same sentence as RACK1 in open-access papers (continued):
Sharing a sentence is not in itself a finding about the gene and the disease.
brain tumors (1 paper, 2021). "Interestingly, according to the Cancer Genome Atlas (TCGA) database, we found that the gene mutation rate of Rack1 in brain tumor samples was about 15.38% (8/52) based on the gene profiling assay (data not shown)." (PMID 34480519, 2021). "Given that the significantly upregulated expression of Rack1 in different subtypes of MB tumors based on our immunostaining and gene profiling assay using GEO DataSet, it would be interesting to ask whether Rack1 gene mutations are involved in the pathogenesis of brain tumors." (PMID 34480519, 2021).
Cognitive impairment (1 paper, 2026). Abnormal cognition is characterized by deficits in thinking, reasoning, or remembering. "This study demonstrates that microglial Rack1 deficiency decreased Aβ deposition and neuroinflammation and ameliorated cognitive impairments in AD model mice by enhancing IGF1‐mediated astrocytic phagocytosis." (PMID 41168999, 2026). "In this study, we demonstrated that microglial Rack1 deficiency decreased Aβ deposition and neuroinflammation and ameliorated cognitive impairments in AD model mice by enhancing IGF1‐mediated astrocytic phagocytosis." (PMID 41168999, 2026). "The conditional knockout of Rack1 in microglia reduced Aβ aggregation, alleviated neuroinflammation, and rescued cognitive impairments in AD model mice." (PMID 41168999, 2026). "We found that the deletion of Rack1 in microglia also reduced Aβ accumulation and attenuated cognitive impairments in AD model mice." (PMID 41168999, 2026). "Together, these findings implied that the conditional knockout of Rack1 in microglia ameliorates cognitive impairment in AD model mice." (PMID 41168999, 2026). "The conditional deletion of microglial Rack1 in the 5×FAD mouse model significantly reduced Aβ accumulation and alleviated cognitive impairment." (PMID 41168999, 2026).
epilepsy (1 paper, 2011). A brain disorder characterized by episodes of abnormally increased neuronal discharge resulting in transient episodes of sensory or motor neurological dysfunction, or psychic dysfunction. "Among these are RACK1 (involved in neuronal excitation), TSC1 (control of axon formation, epilepsy), APP (seizure susceptibility), HSPBAP1 (upregulated in epilepsy patients) and p190 RhoGAPs (involved in neuronal differentiation and process outgrowth)." (PMID 22016787, 2011).
fatty liver disease (1 paper, 2024). A reversible condition wherein large vacuoles of triglyceride fat accumulate in liver cells via the process of steatosis. "Our RibosomeR analysis further suggests the functional relevance of tissue-specific heterogeneity, exemplified by the involvement of RACK1 and MDM2 in adipogenesis and fatty liver disease." (PMID 39086661, 2024). "Notably, RACK1 regulates adipogenesis, while MDM2 promotes the onset of fatty liver disease, both relevant to adipose tissue function." (PMID 39086661, 2024).
female sterility (1 paper, 2021). "Mutants of the essential Drosophila Rack1 gene are known to cause female sterility, but its association with male sterility has not yet been known." (PMID 34849808, 2021).
gestational hypertension (1 paper, 2025). "However, this possible link requires further study, where exposure to different phthalates, placentation, vascular contractility, gestational hypertension, and RACK1 should be analyzed." (PMID 40863334, 2025).
Hepatitis (1 paper, 2017). Inflammation of the liver. "Various cytokines, including IFN-γ and TNF-α, are involved in the pathogenesis of Con A-induced hepatitis, so we wondered whether RACK1 deficiency affects cytokine production." (PMID 28572806, 2017).
hypertensive disorder (1 paper, 2025). Persistently high systemic arterial blood pressure. "A possible connection between hypertensive disorders in pregnancy and phthalates exposure may be related to the modulation of RACK1 expression, particularly at the placental level." (PMID 40863334, 2025).
Hypoglycemia (1 paper, 2013). A decreased concentration of glucose in the blood. "In this study, we demonstrated that VHL-inactivated hepatocytes had enhanced IGF-IR protein expression concomitant with enhanced IGF-IR and RACK1 interactions and glucose uptake in the liver, which resulted in severe hypoglycemia." (PMID 23874892, 2013). "Based on the previous reports and our data, we postulated that hepatic VHL deletion activated an IGF-IR pathway through an accelerated complex formation with RACK1 and contributed to severe hypoglycemia." (PMID 23874892, 2013).
in situ carcinoma (1 paper, 2017). A malignant epithelial neoplasm which is confined to the epithelial layer without evidence of further tissue invasion. "RACK1 and MCM7 expression were higher in in situ carcinoma and cancer cells than in normal bronchial epithelium cells." (PMID 28465488, 2017).
inflammatory bowel disease (1 paper, 2025). A spectrum of small and large bowel inflammatory diseases of unknown etiology. "Given the role of Receptor for Activated C Kinase 1 (RACK1) in both immune cell activation and in the maintenance of the intestinal epithelial barrier integrity, we investigated whether it was involved in inflammatory bowel disease (IBD)." (PMID 39693354, 2025).
iron deficiency (1 paper, 2025). "Prominent hubs within the network included Cp, Ftl1, CD9, and RACK1, suggesting their central roles in orchestrating the astrocyte response to iron deficiency." (PMID 40590312, 2025).
ischemia (1 paper, 2013). A hypoperfusion of the BLOOD through an organ or tissue caused by a PATHOLOGIC CONSTRICTION or obstruction of its BLOOD VESSELS, or an absence of BLOOD CIRCULATION. "However, the inhibition of TNF-αR attenuated the nSMase2 activity to some extent, suggesting that the TNF-αR/RACK1/EED pathway plays a secondary role in the upregulation of nSMase2 activity in hippocampal astrocytes following ischemia." (PMID 24007266, 2013).
ischemia reperfusion injury (1 paper, 2024). Adverse functional, metabolic, or structural changes in ischemic tissues resulting from the restoration of blood flow to the tissue (reperfusion), including swelling; hemorrhage; necrosis; and damage from free radicals. "In hepatic ischemia-reperfusion injury, the receptor for activated C kinase 1 (RACK1) directly interacts with AMPKα to regulate its phosphorylation at the Thr172 site, thereby modulating system Xc− activity." (PMID 39717848, 2024).
lung squamous cell carcinoma (1 paper, 2021). "In this article, we investigated the effect of the FGFR/RACK1 complex on cellular senescence in lung squamous cell carcinomas and determined the underlying mechanism." (PMID 33710818, 2021).
lymphopenia (1 paper, 2017). Reduction in the number of lymphocytes. "Our data indicate that specific deletion of RACK1 in T cells leads to peripheral T cell lymphopenia and impaired iNKT cell development." (PMID 28572806, 2017).
malaria (1 paper, 2024). Malaria is a serious and sometimes fatal disease caused by a parasite that commonly infects a certain type of mosquito which feeds on humans. "To explore the functional role of RACK1 in CD4+ T cell-mediated immunity to blood-stage malaria, we employed a murine model caused by P. yoelii 17XNL, in which CD4+ T cell-dependent immunity is responsible for full resolution of the infection." (PMID 39024388, 2024). "In summary, we have elucidated the biological effects of RACK1 on CD4+ T cell responses and subsequent humoral immunity in a murine malaria model." (PMID 39024388, 2024). "Recent work has highlighted the importance of Tfh cells in immune resistance to blood-stage malaria, we then asked whether lack of RACK1 in CD4+ T cells resulted in phenotypic abnormality of the Tfh compartment." (PMID 39024388, 2024).
medulloblastoma (1 paper, 2021). A malignant, invasive embryonal neoplasm arising from the cerebellum. "Genetic ablation of Rack1 in SHH‐subtype medulloblastoma (MB) tumor mice could significantly reduce tumor cell proliferation, reduce the tumor size, and prolong the survival of tumor rescue mice, indicating that Rack1 may serve as a potential novel therapeutic target for SHH‐type MB in the clinic." (PMID 34480519, 2021).
memory impairment (1 paper, 2022). "Deficits in RACK1 have been previously linked to memory impairment." (PMID 36010666, 2022).
meningioma (1 paper, 2024). A generally slow growing tumor attached to the dura mater. "Our findings indicate that RACK1 expression levels were higher in meningiomas with a greater degree of malignancy, and that there were significant differences in RACK1 levels among the different WHO grades." (PMID 38398158, 2024). "The RACK1 inhibitor, harringtonolide (HA), significantly suppressed the malignant tendencies of meningioma cells." (PMID 38398158, 2024). "To explore how RACK1 affects the malignant progression of meningioma cells, we sequenced the transcriptome of IOMM-LEE cells and IOMM-LEE cells with RACK1 knockdown." (PMID 38398158, 2024). "Our study found that in malignant meningioma cells, RACK1 interacts with CSNK2B and inhibits its ubiquitination and degradation by binding to it." (PMID 38398158, 2024). "We discovered a positive correlation between meningioma malignancy and the levels of the receptor for activated C kinase 1 (RACK1), which interacts with CSNK2B, the β subunit of casein kinase 2 (CK2), inhibiting its ubiquitination and subsequent degradation." (PMID 38398158, 2024). "Transcriptome sequencing data analysis revealed that RACK1 knockdown significantly downregulated the cell cycle pathway in meningioma cells, with CDK4 and cyclin D3 being the most affected." (PMID 38398158, 2024). "Subsequently, we examined the effect of RACK1 on the cell cycle of meningioma cells using flow cytometry." (PMID 38398158, 2024). "To investigate the effect of CSNK2B on the behavior of meningioma cells, we altered the expression of RACK1 and CSNK2B in IOMM-LEE and CH157-MN cells." (PMID 38398158, 2024). "To investigate the correlation between RACK1 expression and the malignancy of meningiomas, we collected tumor tissues from meningiomas of various WHO grades for immunohistochemical and HE staining." (PMID 38398158, 2024). "Moreover, we found that the inhibition of RACK1 using Harringtonolide (HA) inhibits the progression of malignant meningiomas." (PMID 38398158, 2024). "We found a significant correlation between the malignancy of meningiomas and the expression level of RACK1, a scaffolding protein that anchors and maintains structural stability for other proteins and is known to interact with various kinases to regulate multiple signaling pathways." (PMID 38398158, 2024). "Additionally, the subcutaneous implantation of tumors in nude mice showed that, compared to the control group, meningioma cells with RACK1 knockdown formed smaller tumors, while those overexpressing CSNK2B developed larger tumors." (PMID 38398158, 2024). "Consequently, we aimed to investigate the role of RACK1 in the malignant progression of meningiomas and to determine its effects on this process." (PMID 38398158, 2024). "Then, using cycloheximide (CHX) to inhibit protein synthesis, we observed by Western blot that CSNK2B degradation was significantly accelerated in meningioma cells with RACK1 knockdown, whereas degradation was significantly slowed in those cells overexpressing RACK1." (PMID 38398158, 2024). "As we discovered, RACK1 expression is elevated in more malignant meningiomas." (PMID 38398158, 2024). "Furthermore, HA, an inhibitor of RACK1, significantly inhibited the promotion of RACK1 on the malignancy of meningiomas." (PMID 38398158, 2024). "Our study suggests that RACK1 may play a role in the malignant progression of meningiomas, and therefore, targeting RACK1 could emerge as an effective strategy for reducing the malignancy of these tumors." (PMID 38398158, 2024). "Furthermore, flow cytometry revealed that CSNK2B knockdown attenuated the effects of RACK1 overexpression on the meningioma cell cycle." (PMID 38398158, 2024). "In our study, inhibiting RACK1 and CSNK2B expression significantly suppressed the proliferation and migration ability of meningioma cells." (PMID 38398158, 2024).
meningioma (continued). "We altered RACK1 expression in the IOMM-LEE and CH157-MN cells, which are widely utilized human malignant meningioma cell lines, through knockdown and overexpression, respectively." (PMID 38398158, 2024). "Harringtonolide (HA) is a RACK1 inhibitor, and while some studies have demonstrated its potential anti-tumor effects, its effects on meningiomas have not been studied." (PMID 38398158, 2024). "However, the role of RACK1 in meningiomas has not yet been explored." (PMID 38398158, 2024). "RACK1 and CSNK2B have been shown to promote tumor progression but their roles in meningiomas are not clear." (PMID 38398158, 2024).
mesothelioma (1 paper, 2015). A usually malignant and aggressive neoplasm of the mesothelium which is often associated with exposure to asbestos. "We data-mined on mesothelioma datasets the expression of PKCβ (PRKCB), the favoured RACK1 partner." (PMID 26462016, 2015).
metastatic melanoma (1 paper, 2008). A melanoma that has spread from its primary site to another anatomic site. "In our SAGE analysis, the RACK1 tag was more abundant in the library established from primary culture of metastatic melanoma cells than in the library from normal skin melanocytes." (PMID 18442364, 2008). "This study shows that RACK1 mRNA and its corresponding protein are systematically overexpressed in tumoral cells of cutaneous and metastatic melanomas." (PMID 18442364, 2008). "We studied the expression of RACK1 by immunofluorescence and confocal microscopy in tissues specimens of normal skin, in cutaneous and metastatic melanoma developped in MeLiM minipigs and in human patients." (PMID 18442364, 2008).
nevus (1 paper, 2008). Nevus (or naevus, plural nevi or naevi, from nævus, Latin for "birthmark") is the medical term for sharply circumscribed[1] and chronic lesions of the skin or mucosa. "In nevi, RACK1 signal was heterogenous within a given nevus and between nevi showing two patterns: in 7 out of 14 nevi, RACK1 signal was either not detectable (arrowheads) or faint (arrow)." (PMID 18442364, 2008).
Obesity (1 paper, 2013). Accumulation of substantial excess body fat. "The 3T3-L1 adipocyte glycogen proteome consists of enzymes essential for its synthesis together with specific regulatory proteins PPP1R6, RACK1 and the family of 14-3-3 protein isoforms, the most abundant of which have been associated with obesity." (PMID 23521774, 2013).
oral carcinoma (1 paper, 2022). "In addition, PER1 was reported to get involved in glycolysis and glucose uptake in oral carcinoma, which in turn regulate cell viability by targeting RACK1-based complex." (PMID 35140788, 2022).
ovarian tumor (1 paper, 2023). "Previous studies have shown that RACK1 is a powerful tumor-promoting factor in OC, so we investigated whether SMURF2 inhibited the occurrence of ovarian tumors by regulating RACK1." (PMID 37828084, 2023). "Given that abnormally low SMURF2 expression is responsible for elevated RACK1 levels and ovarian tumor progression, our results suggest that targeting RACK1 in patients with abnormally low SMURF2 expression may be a viable stratified treatment approach." (PMID 37828084, 2023).
parasitemia (1 paper, 2024). "By contrast, RACK1 KO mice displayed a similar peak parasitemia at day 17 p.i., but suffered from unremitting hyperparasitemia at the later stage, and all succumbed to the infection by day 35 p.i.." (PMID 39024388, 2024). "Likely, the simultaneously reduced nTreg and IFN-γ (or IL-17A)-secreting CD4+ T cells may considerably explain the comparable parasitemia in WT versus RACK1 KO mice during the early phase of infection." (PMID 39024388, 2024).
proteinopathy (1 paper, 2023). "We provide proof-of-concept evidence for targeting RACK1 as a potential therapeutic approach for TDP-43 or FUS proteinopathy associated with ALS and FTLD." (PMID 38111057, 2023).
renal cell carcinoma (1 paper, 2016). "Besides, RACK1 can modulate PI3K/Akt signaling or activates Akt to propel cell proliferation and invasion/metastasis in VEGF/Flt1-mediated endothelial cells, mouse hepatocarcinoma cells, renal cell carcinoma, and some other cancers." (PMID 27170279, 2016).
renal fibrosis (1 paper, 2024). A final common manifestation of a wide variety of chronic kidney diseases characterized by glomerulosclerosis and tubulointerstitial fibrosis. "On the basis of our findings, we propose that c-Abl promotes renal fibrosis through the maintenance of RACK1 protein stability." (PMID 38689280, 2024). "Subsequently, we demonstrated that RACK1 is indispensable for c-Abl-induced renal fibrosis by promoting FAK activity and FMT progression." (PMID 38689280, 2024). "Collectively, our findings suggest that the c-Abl-RACK1-FAK signaling axis promotes FMT by inducing focal adhesion maturation and stress fiber assembly, representing a novel molecular mechanism underlying the pathogenesis of renal fibrosis." (PMID 38689280, 2024). "Mechanistically, c-Abl maintains the stability of the RACK1 protein, which serves as a scaffold for proteins such as c-Abl and focal adhesion kinase at focal adhesions, driving fibroblast activation and differentiation during renal fibrosis." (PMID 38689280, 2024). "Next, the expression of RACK1 was significantly increased in fibrotic kidneys compared to that in CL kidneys and was colocalized with PDGFRα+ mesenchymal cells and αSMA+ or Col1a1+ myofibroblasts in fibrotic kidneys, implying that RACK1 may play a crucial role in FMT during renal fibrosis." (PMID 38689280, 2024).
Sepsis (1 paper, 2025). Sepsis is defined as life-threatening organ dysfunction caused by a dysregulated host response to infection. "Furthermore, a separate study demonstrated that rosmarinic acid (RA) inhibits lipopolysaccharide (LPS)-induced or sepsis-induced microglial M1 polarization in sepsis-surviving mice via the RACK1/HIF-1α pathway." (PMID 41296787, 2025).
sterility (1 paper, 2010). "rack-1 might affect oogenesis or spermatogenesis, but the nature of this sterility has not been explored." (PMID 21124943, 2010).
vitiligo (1 paper, 2021). Generalized well circumscribed patches of leukoderma that are generally distributed over symmetric body locations and is due to autoimmune destruction of melanocytes. "We discovered that Fam114A1 is closely related to the growth of vitiligo melanocytes by affecting the proliferation, apoptosis, migration, and melanin synthesis of melanocytes and has a reverse effect on the expression of RACK1 protein." (PMID 34837888, 2021). "In addition, hormonal levels are important in the development of vitiligo, while RACK1 expression is heavily dependent on hormonal levels." (PMID 34837888, 2021). "According to these theories, we believe that the negative regulation of RACK1 protein through Fam114A1 protein may have a role in the pathogenesis of vitiligo." (PMID 34837888, 2021).
Yersinia infections (1 paper, 2011). "To gain further insight into the importance of YopK and the interaction with RACK1 for Y. pseudotuberculosis virulence, we took advantage of the new in vivo imaging system technology that allows real-time monitoring of Yersinia infections." (PMID 21347310, 2011).
ZIKV infection (1 paper, 2020). "Our study emphasizes the involvement of both STAT1 and RACK1 in the immune response elicited by the ZIKV infection, suggesting ZIKV might employ a similar approach to suppress the host immune response." (PMID 32753727, 2020).